TH (tyrosine hydroxylase)
Diseases named in the same sentence as TH in open-access papers (continued):
Sharing a sentence is not in itself a finding about the gene and the disease.
gestational diabetes (1 paper, 2023). Carbohydrate intolerance first diagnosed during pregnancy. "In this study, we investigated the effect of gestational diabetes on the expression of the Dopamine (DA) metabolism genes, tyrosine hydroxylase (TH), and dopa decarboxylase (DDC) in the olfactory bulb (OB) tissue of rats’ offspring." (PMID 37970447, 2023). "In this study, we evaluated the number of dopaminergic neurons in the OB tissue by examining the expression of TH and DDC in the OB tissue of the offspring of mothers with gestational diabetes and the control group using qRT-PCR and western blot analysis." (PMID 37970447, 2023).
glaucoma (1 paper, 2020). Increased pressure in the eyeball due to obstruction of the outflow of aqueous humor. "Its activity inhibits tyrosine hydroxylase, which would explain the increased concentration of tyrosine in the glaucoma signature." (PMID 32012845, 2020).
Headache (1 paper, 2023). Cephalgia, or pain sensed in various parts of the head, not confined to the area of distribution of any nerve. "Unraveling the mechanism of influence of dual TH+/CGRP+ immunoreactive neurons in the A11 nucleus is significant for understanding headache transmission." (PMID 38069205, 2023).
hemochromatosis (1 paper, 2023). A disorder of iron metabolism characterized by a triad of HEMOSIDEROSIS; LIVER CIRRHOSIS; and DIABETES MELLITUS. "Genetic disorders affecting iron metabolism, transport, storage and cellular handling (e.g., β-Thalassemia) also disturb TH status, and diagnostic procedures for TH determination and the adverse impact of hemochromatosis on thyroid function has been known since 1936." (PMID 36834802, 2023).
Hepatic steatosis (1 paper, 2025). Steatosis is a term used to denote lipid accumulation within hepatocytes. "This neural circuit influences hepatic lipid acquisition, and inhibition of ER stress in these neurons reduced liver triglyceride levels and tyrosine hydroxylase (TH, a marker of sympathetic activity), confirming the neurogenic contribution to hepatic steatosis." (PMID 41463101, 2025).
hepatocellular carcinoma (1 paper, 2024). A malignant tumor that arises from hepatocytes. "The mRNA expression level of TH in the majority of hepatocellular carcinoma cell lines, including QGY7701, PVTT, MHCC97H, and QGY, was shown to be lower compared to the normal hepatic cell line, HHL5." (PMID 38610044, 2024).
heroin dependence (1 paper, 2020). Physical and psychological dependence on the drug heroin. "This study aimed to identify the association between genetic polymorphisms of DA synthesis and metabolism genes, including tyrosine hydroxylase (TH), DOPA decarboxylase (DDC), solute carrier family 6 member 3 (SLC6A3) and DA beta-hydroxylase (DBH), with six important phenotypes of heroin dependence." (PMID 32736537, 2020).
Hyperammonemia (1 paper, 2024). An increased concentration of ammonia in the blood. "Movement disorder in ASA is, at least partially, not related to hyperammonemia as demonstrated in a knockout Asl model in dopaminergic neurons, Aslflox/flox;TH Cre+/− mouse." (PMID 38044746, 2024).
hyperprolactinemia (1 paper, 2015). Abnormally high level of prolactin in the blood. "Hyperprolactinemia leads to increased expression of tyrosine hydroxylase mRNA in regions of the hypothalamus associated with sexual and erectile function." (PMID 25844161, 2015).
Hypoinsulinemia (1 paper, 2020). A decreased concentration of insulin in the blood. "In the pathogenesis and progression of PD and DM, insulin and dopamine are regulated mutually, and hypoinsulinemia induced by streptozotocin can reduce the levels of dopamine transporter (DAT) and tyrosine hydroxylase (TH) transcription in the substantia nigra pars compacta." (PMID 32760240, 2020).
infertile (1 paper, 2015). "In our previous study, random distribution and depletion of H3K9ac interaction in many loci (for example, CTSD, FLNA, MCF2L, PLXNA3, SG3GLB2, TH) of infertile men sperm have been confirmed." (PMID 25806092, 2015).
insulinoma (1 paper, 2020). "Conversely, the significantly opposite methylation and expression changes exemplified by LSP1, H19, TH, KCNQ1, SLC22A18, OSBPL5 are thus more likely random and unrelated to insulinoma pathogenesis." (PMID 33060578, 2020).
kidney injury (1 paper, 2024). Trauma to the kidney. "Following kidney injury, the activation of PVN(→RVLM) neurons occurs, leading to an increase in the number of TH-positive neurons in the RVLM." (PMID 39346076, 2024).
lung carcinoma (1 paper, 2024). "Taken together, this suggests that dopaminergic innervation is unlikely to account for the increased secretion of dopamine observed in adult human lung cancer cells, but instead that it could be due to aberrant upregulation of TH and DDC in lung cancer." (PMID 38572507, 2024).
lung diseases (1 paper, 2017). "Previous studies suggest that ADRB2, GNB3, TH, and GSTP1 polymorphisms are associated with various lung diseases." (PMID 28212552, 2017).
melanism (1 paper, 2015). "Thus, our finding of TH overexpression as the major contributor to the pupal melanism of S. exigua also represents the first report of the involvement of TH in insect melanism mutation." (PMID 26084938, 2015).
muscular atrophy (1 paper, 2020). The loss of muscle tissue due to inactivity or disease. "Meanwhile, we found that compared with 1-month-old TH-null mice, 12-month-old mice had more obvious muscular atrophy of the PFM, and MVD exacerbated this damage." (PMID 32332705, 2020).
neuritis (1 paper, 2024). A neuropathy arising from inflammation of one or more nerves. "It was found that, compared with the untreated control culture, CCl4 (2.5 mM on day 12 in vitro for 48 hours) significantly reduced the number of tyrosine hydroxylase (TH+) cells by 51% and reduced the length of neuritis and leaded to truncated degradation of cell morphology." (PMID 40190514, 2024).
neuroblastic tumor (1 paper, 2018). A group of nervous system tumors which display neuronal differentiation. "TH-MYCN mice express the human MYCN gene under the control of the rat tyrosine hydroxylase (Th) promotor, which results in neuroblastic tumors in about 50% of transgenic animals." (PMID 29492199, 2018).
Neurodegeneration (1 paper, 2022). Progressive loss of neural cells and tissue. "Second, it is a common observation in multiple neurodegeneration diseases that TH may lose immunoreactivity without a concomitant loss of dopamine neurons." (PMID 34983390, 2022).
neurodevelopmental disabilities (1 paper, 2009). "Therefore, we concluded that transactivation of the TH gene is one of the first molecular events of neurodevelopmental disabilities after exposure to TCDD." (PMID 19500377, 2009).
neuronal tumor (1 paper, 2015). Neuronal brain tumors are an uncommon group of central nervous system tumors that arise from cells with neuronal differentiation. "We also verified these observations in a cell line of neuronal origin: CAD cells are derived from neuronal tumor cells arising in transgenic mice in which the SV40 large T antigen was placed under the control of the tyrosine hydroxylase promoter." (PMID 25869136, 2015).
Nocardia infection (1 paper, 2022). "The tyrosine hydroxylase (TH) in the striatum of the mouse brain was significantly reduced after infection, further indicating that Nocardia infection could cause a decrease in striatal dopamine content, which in turn led to PD-like neurological symptoms." (PMID 36352407, 2022).
Pain (1 paper, 2025). An unpleasant sensory and emotional experience associated with actual or potential tissue damage, or described in terms of such damage. "Specifically, TH+Kv7.2 expression was significantly lower than TH+Kv7.3 (−51.1%*, p=0.0378), TH+Kv7.4 (−55.9%, **p=0.0059), and TH+Kv7.5 (−55.1%, **p=0.0082), suggesting VTA dopamine neurons exhibit low basal Kv7.2 expression and a heightened expression during chronic neuropathic pain." (PMID 40631219, 2025).
periodontal disease (1 paper, 2021). "Tyrosine hydroxylase (TH) catalyzes the rate-limiting step in the synthesis of catecholamines and is associated with increased periodontal disease progression under chronic stress." (PMID 34948136, 2021).
pituitary tumor (1 paper, 2020). A benign or malignant neoplasm affecting the pituitary gland. "adenovirus-mediated delivery of tyrosine hydroxylase reduces pituitary growth and circulating prolactin levels in a model of estrogen-induced pituitary tumors in rats." (PMID 32201880, 2020).
pterygium (1 paper, 2025). A wedge-shaped fibrovascular lesion arising from the bulbar conjunctiva and extending to the cornea. "The increased expression of TH, ADRA1A, ADRA1B, and ADRB2 suggests the involvement of the sympathetic system in the pathogenesis of pterygium." (PMID 40806545, 2025).
pulmonary edema (1 paper, 2015). Accumulation of fluid in the lung tissues causing disturbance of the gas exchange that may lead to respiratory failure. "Contrasting reports, however, persist regarding TH polymorphism: while its association was reported with development of high altitude pulmonary edema through inadequate hypoxic ventilatory response, in a subsequent study in the Japanese population no such association was found." (PMID 26373931, 2015).
Rett syndrome (1 paper, 2022). A severe neurodevelopmental disorder affecting the central nervous system.
rickets (1 paper, 2010). Bone softening and weakening usually caused by deficiency or impaired metabolism of vitamin D. Deficiency of calcium, magnesium, or phosphorus may also cause rickets. "Recently, post-eclosion tanning has been linked to phosphorylation of tyrosine hydroxylase (TH) by PKA, as a result of rickets activation." (PMID 20807433, 2010).
Rotavirus infection (1 paper, 2022). Infection with any of the rotaviruses. "We demonstrate that rotavirus infection of the small intestine presymptomatically disrupts the autonomic balance by downregulating tyrosine hydroxylase in the noradrenergic sympathetic nervous system in the ileum, concomitant with increased intestinal transit." (PMID 36094089, 2022). "Rotavirus infection induces downregulation of tyrosine hydroxylase in noradrenergic sympathetic neurons of the ileum." (PMID 36094089, 2022). "As rotavirus-infected animals showed downregulation of TH in sympathetic nerves, we hypothesized that the CNS partly controls intestinal motility through downregulation of TH during rotavirus infection." (PMID 36094089, 2022). "We showed and quantified the extent of rotavirus infection of the small intestine by 3D imaging and identified centrally relayed downregulation of TH in the sympathetic innervation of the ileum, concomitant with increased intestinal transit and altered brain activity before the onset of diarrhea." (PMID 36094089, 2022).
sickle cell disease (1 paper, 2016). Sickle cell anemias are chronic hemolytic diseases that may induce three types of acute accidents: severe anemia, severe bacterial infections, and ischemic vasoocclusive accidents (VOA) caused by sickle-shaped red blood cells obstructing small blood vessels and capillaries. "The neurogenic contractions were higher in the sickle cell disease group, in association with elevated tyrosine hydroxylase phosphorylated at Ser-31 and total tyrosine hydroxylase protein expression, as well as increased tyrosine hydroxylase mRNA expression." (PMID 27935981, 2016).
thymoma (1 paper, 2026). A neoplasm arising from the epithelial cells of the thymus. "In thymomas, the transcript levels of autoantigens that are frequently targeted by autoantibodies (CYP21, CYP17, TPH1, TH, TPO) did not correlate with AIRE expression." (PMID 41461613, 2026).
thyroid nodule (1 paper, 2020). A small circumscribed mass in the THYROID GLAND that can be of neoplastic growth or non-neoplastic abnormality. "In addition, the case history of patient #2 illustrates the fact that permanently suppressed TSH levels following pituitary surgery, in combination with detectable TH levels while not on thyroxine therapy, may denote the presence of concomitant, but previously hidden autonomous thyroid nodules." (PMID 32733382, 2020).
Tinnitus (1 paper, 2022). Tinnitus is an auditory perception that can be described as the experience of sound, in the ear or in the head, in the absence of external acoustic stimulation. "The number of PH8-positive cells was reduced in the DRN and ROb of tinnitus patients compared to controls, while the number of TH-positive cells remained unchanged in the DRN." (PMID 36009087, 2022).
TSHomas (1 paper, 2022). "SITSH is mainly caused by TSHomas secreting excessive TSH or syndromes of resistance to thyroid hormone (RTH), causing the pituitary gland to be insensitive to TH." (PMID 36619586, 2022).
tyrosinemia (1 paper, 2023). An autosomal recessive inherited metabolic disorder caused by mutations in the FAH, HPD, and TAT genes. "The rare IEM disorder tyrosinemia occurs due to the accumulation of Tyr in the body, which is also caused by a mutation in the gene-expressing enzyme tyrosine hydroxylase (TyH), which catabolizes Tyr." (PMID 37511898, 2023).
Zinc deficiency (1 paper, 2021). A deficiency of the essential metal Zinc; an essential cofactor for many enzymes. "Since Catsup is responsible for zinc release from the secretary pathway to cytoplasm, Catsup mutations lead to zinc deficiency in the cytoplasm, and in consequence, more iron could bind to TH, resulting in the increased TH activity." (PMID 34732185, 2021).
tumor (81 papers, 2003 to 2025). "In our study, we have demonstrated that TH, acting as the key synthetase of dopamine, was aberrantly overexpressed in EC tumor tissue, causing the accumulation of dopamine." (PMID 33898321, 2021). "primary cultures of human lactotroph tumor cells were transfected with an adenovirus vector containing a cDNA encoding a human tyrosine hydroxylase: transfection induced increased production of dopamine, resulting in the predicted biologic effect of decreased prolactin secretion." (PMID 32201880, 2020). "Tyrosine hydroxylase is involved in the first step of catecholamine biosynthesis, a unique feature similar to melanin biosynthesis in melanoma, involving enzymes restricted to the tumor tissue therefore providing tumor-associated antigens." (PMID 21197271, 2010). "Our findings showed that the expression level of ADRB2 and TH in tumor tissues of sleep-deprived mice was significantly higher than those in the normal sleep group, while the expression levels of ADRA1, ADRA2, ADRB1, and ADRB3 showed no significant changes." (PMID 40276761, 2025). "To validate the activation of sympathetic nervous system in the tumor tissue, we observed a significant upregulation of sympathetic nerve marker tyrosine hydroxylase (TH) expression in the tumor tissue of sleep-deprived mice." (PMID 40276761, 2025). "To investigate the potential activation of catecholaminergic neurons in the RVLM of tumor-bearing mice due to sleep deprivation, we conducted an immunofluorescence assay to assess the expression of TH and the neuron activation marker cFos in the RVLM region." (PMID 40276761, 2025). "The results revealed a significant activation of TH-immunoreactive neurons in response to sleep deprivation in tumor-bearing mice." (PMID 40276761, 2025). "To further confirm this phenomenon, we performed immunofluorescence staining on tumor sections using TH, VAChT, and neurofilament‐heavy (NF‐H) antibodies to quantify nerve fiber density." (PMID 40488319, 2025). "Tumor tissues were co‐stained with tyrosine hydroxylase (TH), a sympathetic‐neuronal marker, and vesicular acetylcholine transporter (VAChT), a parasympathetic‐neuronal marker." (PMID 40488319, 2025). "The protein expression level of TH measured by western blot consistent with IHC assay, 17/17 of tumor tissues shown down-regulated compare with adjacent non-tumor haptic tissues." (PMID 38610044, 2024). "The protein expression level of TH in the HCC tissues was found to be lower than that in the adjacent non-tumor tissues." (PMID 38610044, 2024). "Subsequently, immunohistochemistry (IHC) was utilized to quantify the levels of TH protein expression in a human HCC tissue array consisting of 198 HCC samples together with their corresponding adjacent non-tumor tissues." (PMID 38610044, 2024). "Although most sympathetic PCPG are biochemically active, a small number of A5 cases had normal catecholamine levels and such tumours also had low TH expression." (PMID 38978571, 2024). "In this study, we identified a new signaling regulatory mechanism, namely the DRD2/ERK/β-catenin pathway and Dopamine/ERK/TH regulatory loop, which was activated by chronic stress and in turn promoted tumor progression." (PMID 37415171, 2023). "Tumors displayed an undifferentiated morphology, were positive for the NB marker PHOX2B, and maintained high amounts of MES markers SOX9 and LGR5 along with low ADR marker TH, in concordance with the parental relapse tumor." (PMID 36306349, 2022). "Having determined that synaptophysin and, to a lesser extent, tyrosine hydroxylase are useful chromaffin cell markers in PPGL tumour cultures, we assessed the expression of these and other markers in a selection of short and long-term cultures." (PMID 36178902, 2022). "Immunohistochemical analysis indicated that the tumor appeared to be co-positive with tyrosine hydroxylase (TH) as well as ACTH in most tumor cells in both PCC and liver metastasis." (PMID 35854271, 2022).